TXNIP (thioredoxin interacting protein)
Diseases named in the same sentence as TXNIP in open-access papers (continued):
Sharing a sentence is not in itself a finding about the gene and the disease.
breast tumors (4 papers, 2010 to 2023). "Similar to our findings that miR-342 sensitizes breast tumor cells to tamoxifen, TXNIP sensitizes breast tumor cells to paclitaxel." (PMID 21172025, 2010). "Accordingly, TXNIP expression is induced in tumor cells by various stresses including serum starvation, which mimics ERα inactivation in breast tumors, and enhanced TXNIP expression has tumor-suppressor activity." (PMID 21172025, 2010). "Our functional assays suggest that RocA or similar translation inhibitors may show efficacy against ER− breast tumors and that the levels of MondoA and TXNIP should be considered when exploring these potential treatment options." (PMID 33292639, 2020). "Together, our data suggest that TXNIP is capable of regulating Myc transcriptional programs, not only in cell lines, but in bona fide breast tumors as well." (PMID 36930677, 2023). "Further, it suggests that TXNIP and TXNRD1 are ERBB2 effectors whose multiple cellular functions contribute to proliferation, apoptosis resistance, metabolic reprogramming and, finally, to the hallmarks of ERBB2-positive breast tumors." (PMID 20584310, 2010).
COVID-19 (4 papers, 2021 to 2023). A disease caused by infection with severe acute respiratory syndrome coronavirus 2. "MiRNAs that were downregulated in serum of COVID-19 patients mainly target genes promoting angiogenesis (e.g., VEGFA, ANGPT2, COL4A1, FGF2, ZEB1), apoptosis, autophagy, stress response (e.g., ATG12, ATG14, ATG2B, SOD2, TXNIP), and inflammation (e.g., CXCL9, CXCL10, IL1R1, TNF)." (PMID 36032130, 2022). "Consistently, proteomic and metabolomics data from CMs revealed several genes (KNG1, TXNIP, ITIH4, TIMP1, SERPING1/2/3, ITGA1, ADAR, and CLIC5 etc.)and molecules (adenosine and inosine) were related with platelet activation, thus, adding antiplatelet might be a possible therapeutic for COVID-19." (PMID 35903092, 2022).
gouty arthritis (4 papers, 2018 to 2025). "Recently, TXNIP, a known negative regulator of antioxidative protein thioredoxin, has emerged to be an attractive target in gouty arthritis, cervical inflammation, and CNS-related injury or diseases, implicating TXNIP as an important player in their pathogenesis." (PMID 29386025, 2018). "For example, in a murine model of gouty arthritis, the compound was found to inhibit the IKK/NF-κB/TXNIP axis, leading to downregulation of NLRP3 and pro-IL-1β expression, ultimately attenuating inflammation and monocyte infiltration." (PMID 41463396, 2025). "Collectively, these results demonstrated that corilagin suppressed the ROS/TXNIP/NLRP3 pathway to repress inflammasome activation and pyroptosis and suggest its potential antioxidative role in alleviating NLRP3-dependent gouty arthritis." (PMID 36299604, 2022). "Our results illustrate that corilagin restricts ROS/TXNIP/NLRP3 pathway to diminish macrophage pyroptosis and proinflammatory cytokines release, thereby alleviating NLRP3-dependent gouty arthritis." (PMID 36299604, 2022). "Although corilagin treats gouty arthritis by obstructing the NLRP3 inflammasome, the in vivo function of corilagin in mediating the ROS/TXNIP/NLRP3 pathway remains unclear." (PMID 36299604, 2022). "As a known negative modulator of antioxidant protein thioredoxin, TXNIP has emerged as a promising target in a number of diseases like gouty arthritis, cervical inflammation, and central nervous system-related injuries or diseases." (PMID 35845136, 2022).
heart failure (4 papers, 2013 to 2025). Inability of the heart to pump blood at an adequate rate to meet tissue metabolic requirements. "In this work, we also found that increased expression of lipid peroxidation 4-HNE in the hearts of heart failure mice prompted TXNIP to protect the damaged heart through compensatory elevation." (PMID 40563380, 2025). "Collectively, NLRP3 deletion abrogated TXNIP overexpression‐induced exacerbation of heart failure in obese hearts." (PMID 39604027, 2024). "TXNIP expression was highest in the non-heart failure patients, dropped in expression at 7 days post LVAD and partially recovered by 6 months." (PMID 24205042, 2013). "Mechanistically, TXNIP promotes GSH effects in response to lipid peroxidation in heart failure." (PMID 40563380, 2025). "In the heart failure group, NLRP3, TXNIP, Caspase-1, and IL-1β protein expressions were up-regulated, and aerobic exercise and SKQ1 down-regulated NLRP3, TXNIP, Caspase-1, and IL-1β protein expressions." (PMID 40076760, 2025). "At the same time, TXNIP-mediated NLRP3 activation was decreased, thereby alleviating TAC-induced myocardial inflammation and apoptosis in mice with heart failure." (PMID 40076760, 2025).
inflammatory bowel disease (4 papers, 2022 to 2025). A spectrum of small and large bowel inflammatory diseases of unknown etiology. "Previous studies have shown that LBPs alleviate inflammatory bowel disease by modulating STAT1/STAT6 signaling, and exert hepatoprotective effects by inhibiting thioredoxin-interacting protein (TXNIP) and suppressing NOD-like receptor 3 (NLRP3) inflammasome activation." (PMID 41140831, 2025).
kidney damage (4 papers, 2018 to 2025). "In summary, the present study firstly provides the data that CXCR4/TXNIP is involved in the modulation of the kidney damage via directly regulating NLRP3 inflammasome." (PMID 29849929, 2018). "Blood, urine examination, and renal biopsy demonstrated a marked rise in the expression of TXNIP in DKD patients, and experiments showed that the absence of TXNIP could alleviate kidney damage in DKD mouse models, which proved that TXNIP played an instrumental position in DKD." (PMID 41362412, 2025).
liver fibrosis (4 papers, 2020 to 2025). "We focused on SOCS3, SREBF1, and TXNIP, genes known to be implicated in inflammatory pathways and liver fibrosis." (PMID 39941038, 2025). "The taurine pathway plays an antioxidant role in acute liver failure, and it can inhibit liver injury and liver fibrosis by inhibiting TLR4/NFKB and and TxNiP/NLRP3 pathways." (PMID 36278176, 2022).
osteosarcoma (4 papers, 2020 to 2023). A usually aggressive malignant bone-forming mesenchymal neoplasm, predominantly affecting adolescents and young adults. "CircECE1 interacts with c-Myc to protect it from ubiquitination and degradation, activates c-Myc-TXNIP signalling pathway, boosts glucose uptake, glycolysis, lactate production, and ATP production to facilitate the proliferation and migration of osteosarcoma." (PMID 37599427, 2023). "When circECE1 had been knocked out, TXNIP was significantly increased on both mRNA and protein level; therefore, TXNIP transcription was inhibited in osteosarcoma, and subsequently activated the Warburg Effect." (PMID 37599427, 2023). "The involvement of Ets-1 in the transcriptional activity of TXNIP has previously been reported in studies that observed induction of TXNIP by synthetic retinoids in osteosarcoma cells and in the regulation of TXNIP expression in pancreatic cells." (PMID 35888758, 2022). "CircECE1 activates energy metabolism in osteosarcoma through the c-Myc/TXNIP axis." (PMID 34224315, 2021).
ovarian carcinoma (4 papers, 2018 to 2023). A malignant neoplasm originating from the surface ovarian epithelium. "TXNIP levels predicted progression-free (log-rank p = 0.026) survival in stage 1/2 ovarian cancer and overall survival (log rank p = 0.047) in stage 3/4 ovarian cancer." (PMID 30479697, 2018). "We used the TCGA dataset to determine the prognostic significance of TXNIP expression in early and late stage ovarian cancer patients." (PMID 30479697, 2018). "Ovarian cancer spheroids isolated from patient ascites had significantly higher TXNIP than their attached counterparts (p = 0.047)." (PMID 30479697, 2018). "Conversely, in patients with stage 3 and 4 ovarian cancer, the low TXNIP group exhibited a survival advantage in terms of OS (log-rank p = 0.043)." (PMID 30479697, 2018). "We generated stable knockdowns of TXNIP in the HEYA8 ovarian cancer cell line (HEYA8shTXNIP) with an independent GFP-fluorescent tag." (PMID 30479697, 2018). "In particular, TXNIP was the top outlier in our ovarian cancer cell line (HEYA8)." (PMID 30479697, 2018). "Given the conflicting reported significance for TXNIP in various tumors and the increased expression identified in our outlier analysis of in vitro spheroids, we examined if TXNIP was prognostic in clinical ovarian cancer patient samples." (PMID 30479697, 2018).
stomach cancer (4 papers, 2019 to 2024). "MSC Exos with miR-301-3p stimulates multidrug resistance of gastric tumor cells by inhibiting thioredoxin-interacting protein TXNIP." (PMID 38360641, 2024).
acute lung injury (3 papers, 2022 to 2023). A condition of lung damage that is characterized by bilateral pulmonary infiltrates (pulmonary edema) rich in neutrophils, and in the absence of clinical heart failure. "The mechanism of cell pyroptosis caused by the TXNIP/NLRP3 signal axis has been reported in other diseases, such as intestinal ischemia-reperfusion injury, cadmium-induced liver injury, and LPS-induced acute lung injury." (PMID 38069134, 2023).
acute pancreatitis (3 papers, 2021 to 2022). An acute inflammatory process that leads to necrosis of the pancreatic parenchyma. "We found that pancreatic damage and the inflammatory response associated with acute pancreatitis were largely restrained in TXNIP knock-out mice but were enhanced in mice overexpressing TXNIP." (PMID 36316322, 2022). "In this study, we investigated the role of thioredoxin interacting protein (TXNIP) in acute pancreatitis when induced by high doses of arginine." (PMID 36316322, 2022).
adenoma (3 papers, 2020 to 2024). A neoplasm arising from the epithelium. "In contrast, colo-rectal cancer specimens showed no clear patterning of TXNIP expression: TXNIP-positive tumors were detected in 34.5% of adenocarcinomas, 36.4% of high-grade adenomas, and some weak expression of 55.6% in low-grade adenomas." (PMID 33081035, 2020). "In the LNM-positive group compared to the control adenoma, there were significant increases in gene expression for CCL15, SSX1, and KRT5 genes, alongside significant decreases in HLA-E, ITPK1, ANXA1, and TXNIP genes across the head, proximal stalk, and distal stalk regions." (PMID 38256174, 2024).
bladder (3 papers, 2018 to 2023). "In particular, overexpression of TXNIP attenuates CXCL12-induced bladder carcinogenesis, while knockout of TXNIP enhances CXCR4 expression in bladder carcinogenesis in urothelial cells, indicating an interaction may exist between TXNIP and CXCR4." (PMID 29386025, 2018). "Former researches also showed that CXCL12/CXCR4 axis could regulate bladder carcinogenesis via activating extracellular signal-regulated kinase (ERK), which was subject to TXNIP negative regulation." (PMID 33747959, 2021).
cataract (3 papers, 2018 to 2025). Partial or complete opacity of the crystalline lens of one or both eyes that decreases visual acuity and eventually results in blindness. "Overall, our findings demonstrated the protective ability of NACA to abate aberrant redox-active pathways, particularly the ROS/TRX/TXNIP axis, thereby preventing cataractogenesis and preserving eye lens integrity and ultimately impeding aging-related cataracts." (PMID 40149978, 2025).
chronic myeloid leukemia (3 papers, 2019 to 2025). "Among the other tumors, TXNIP expression is down‐regulated in chronic myeloid leukemia (CML) in response to activated BCR‐ABL fusion protein that stimulates glucose metabolism, mainly by increasing glucose transporter exposure at the plasma membrane." (PMID 39364720, 2025).
diabetic neuropathy (3 papers, 2017 to 2020). A chronic, pathological complication associated with diabetes mellitus, where nerve damages are incurred due to diabetic microvascular injury involving small blood vessels that supply these nerves, resulting in peripheral and/or autonomic nerve dysfunction. "Based on the findings, we proposed that diabetic neuropathy induced by HFD was likely to be associated with TXNIP upregulation." (PMID 30733849, 2019). "Thus, our findings suggest that onset and progression of diabetic neuropathy might be linked to the increased expression of TXNIP." (PMID 30733849, 2019). "In conclusion, this study shows that elevated serum TXNIP, oxidative stress, and inflammation are present in patients with diabetic neuropathy." (PMID 32774321, 2020). "Using HFD-induced diabetic mice and palmitate-treated neurons, we showed that oral verapamil reduced the expression of TXNIP, inhibited the activation of inflammasome, prevented the neuronal apoptotic, and eventually improved diabetic neuropathy." (PMID 30733849, 2019). "In fact, we observed that pharmacological inhibition of TXNIP caused by verapamil, an inhibitor of TXNIP, increased MNCV and SNCV in HFD-fed mice, suggesting that verapamil improved diabetic neuropathy." (PMID 30733849, 2019). "Thus, we show for the first time that TXNIP might be a potential target for the treatment of diabetic neuropathy." (PMID 30733849, 2019). "However, they did not provide the functional evidence that TXNIP upregulation is associated with diabetic neuropathy." (PMID 30733849, 2019).
dilated cardiomyopathy (3 papers, 2021 to 2023). Cardiomyopathy which is characterized by dilation and contractile dysfunction of the left and right ventricles. "The TRX-TXNIP system is disrupted in ischemic cardiomyopathy with reduced TRX and overexpressed TXNIP, but similar features are not evident in dilated cardiomyopathy." (PMID 36830671, 2023). "In ischemic cardiomyopathy, the TRX-TXNIP system is impaired with reduced TRX and overexpressed TXNIP, whereas these features are not observed in dilatated cardiomyopathy." (PMID 33567593, 2021).
endometrial cancer (3 papers, 2020 to 2022). Primary or metastatic malignant neoplasm involving the endometrium (mucous membrane that lines the endometrial cavity). "It has been shown that vitamin D3 can regulate the levels of ROS in endometrial cancer cells by increasing TXNIP expression resulting in an inhibition of human endometrial cancer cell proliferation." (PMID 33194655, 2020).
endometritis (3 papers, 2020 to 2025). An acute or chronic, usually bacterial infectious process affecting the endometrium. "Melatonin downregulates ER-induced TXNIP/NLRP3 pathway in LPS-induced endometritis." (PMID 34202842, 2021). "In addition, melatonin has been found to inhibit endoplasmic reticulum (ER) stress-mediated thioredoxin interacting protein (TXNIP)/NLRP3 inflammasome activation via adenosine monophosphate-activated protein kinase (AMPK) regulation in LPS-induced endometritis." (PMID 40723465, 2025). "In a mouse LPS-induced endometritis model, melatonin reverses neutrophil infiltration and the rise in ROS, ER stress, and protein levels of NLRP3 inflammasome components in endometrial tissue through inhibiting NF-κB and TXNIP and upregulating AMPK." (PMID 34202842, 2021).
glaucoma (3 papers, 2024 to 2025). Increased pressure in the eyeball due to obstruction of the outflow of aqueous humor. "We next analyzed the relationship between TXNIP and microglial phenotype transformation in experimental glaucoma." (PMID 39736512, 2024). "Our study demonstrates the beneficial role of TXNIP inhibition in the context of glaucomatous neurodegeneration and provides a theoretical basis for new breakthroughs in the field of glaucoma treatment." (PMID 39736512, 2024). "Taken together, our findings suggest that TXNIP probably mediates neuroinflammation in experimental glaucoma by activating retinal microglia." (PMID 39736512, 2024). "Our second major finding was that TXNIP mediated the phenotypic change in microglia in experimental glaucoma." (PMID 39736512, 2024). "Our result complemented those of a previous study implying that RGC death was prevented in the absence of TXNIP under retinal neurodegeneration, indicating the possible prospects of TXNIP as a new endogenous therapeutic target for neuroprotection in glaucoma." (PMID 39736512, 2024). "To first investigate the physiopathological function of TXNIP in experimental glaucoma, we applied transcriptome sequencing using the Illumina HiSeq X Ten platform." (PMID 39736512, 2024). "The pathological role of TXNIP was interpreted as regulating microglial activation in experimental glaucoma in our study." (PMID 39736512, 2024). "Although there is evidence suggesting that TXNIP is involved in retinal diseases, little is known about its role in experimental glaucoma." (PMID 39736512, 2024). "Hence, TXNIP shows promise as an endogenous target through which to regulate microglial activation in glaucoma." (PMID 39736512, 2024). "The role of TXNIP in experimental glaucoma may vary and may be related to the time, frequency and degree of sustained high-pressure maintenance." (PMID 39736512, 2024). "Therefore, to explore the specific mechanism underlying the regulation of retinal microglial phenotypic transformation by TXNIP in experimental glaucoma, we screened and verified these two signaling pathways in vitro." (PMID 39736512, 2024). "Taken together, these data suggested that either direct knockout of TXNIP or blockade of the NLRP3 pathway, which is essential for the effect of TXNIP, could exert a neuroprotective effect in experimental glaucoma." (PMID 39736512, 2024). "In addition, we found that ablation of TXNIP promoted retinal ganglion cells (RGCs) survival and alleviated visual function impairment in experimental glaucoma." (PMID 39736512, 2024). "Hence, we speculated that TXNIP might affect the stress reaction of microglia through the PI3K/Akt signaling pathway in experimental glaucoma." (PMID 39736512, 2024). "TXNIP may also be involved in this process by regulating the microglial immune response in synergy with the impact of IL-17A in the early stage of experimental glaucoma." (PMID 39736512, 2024). "Targeting pathways involved in oxidative stress and fibrosis, such as TXNIP, SNAI1, and related signaling pathways, can provide new therapeutic approaches in managing elevated IOP and mitigating glaucoma progression in diabetic patients." (PMID 39764143, 2024). "To the best of our knowledge, we are the first to report that TXNIP affects microglial polarity transformation and glucose uptake through the PI3K/Akt pathway in experimental glaucoma." (PMID 39736512, 2024). "In this study, we induced experimental glaucoma in forms of a mouse model of chronic ocular hypertension (COH) and a pressurized cell culture system for separate observation of retinal microglia to explore the specific role of TXNIP in the relationship with microglial activities." (PMID 39736512, 2024).
Hypercholesterolemia (3 papers, 2022 to 2025). An increased concentration of cholesterol in the blood. "CSA male (p = 0.01) hypertensive (p = 0.005) patients with hypercholesterolemia (p = 0.001) had significantly increased TXNIP expression." (PMID 36830671, 2023). "We conclude that ceramide from ASM plays a critical role in NLRP3 inflammasome activation during hypercholesterolemia via MR redox signaling platforms to produce superoxide, which leads to TXNIP dissociation." (PMID 36252682, 2022). "Our findings may offer novel therapeutic insights into targeting ASM-ceramide-MR redox signaling or TXNIP to suppress the activation of endothelial NLRP3 inflammasomes, thereby preventing and treating vasculopathy associated with hypercholesterolemia." (PMID 36252682, 2022). "In addition, patients with hypercholesterolemia represent high levels of TXNIP expression." (PMID 36830671, 2023).